ACSL5 (acyl-CoA synthetase long chain family member 5)
Diseases named in the same sentence as ACSL5 in open-access papers (continued):
Sharing a sentence is not in itself a finding about the gene and the disease.
tumor (38 papers, 2009 to 2025). "Survival analysis of these genes in tumour samples identified seven genes that were associated with prognosis, including ACSL5, HSD17B11, CCL5, NCF2, PSME1, ACTB, and CYBB." (PMID 40299520, 2025). "ACSL5 expression was inversely associated with Ki67 in low-grade tumours, while ACSL3 was positively associated with Ki67 in high-grade tumours." (PMID 41154605, 2025). "Collectively, dysregulated expression of ACSL1, ACSL4 and ACSL5 isoforms in CRC tissues is associated with tumour progression and patient outcomes, warranting additional research for biomarker development." (PMID 41154605, 2025). "In contrast, low ACSL5 expression in CRC tissues is associated with early tumour recurrence." (PMID 41154605, 2025). "ACSL5 was found to function as an immune-dependent tumor suppressor, and SPDEF and FOXA1 are the canonical markers of mammalian “goblet cells”." (PMID 40429746, 2025). "ACSL5 expression enhances tumor sensitivity to PD-1 blockade therapy in vivo and CD8 + T cell-mediated cytotoxicity in vitro by regulating major histocompatibility complex class I (MHC-I)-mediated antigen presentation." (PMID 40181462, 2025). "ACSL1 and ACSL5 have prognostic significance in gliomas, influencing tumor immunity and immune cell migration, thereby providing valuable insights into low-grade glioma (LGG) prognosis and potential therapeutic targets." (PMID 41288931, 2025). "Critically, ACSL5 promotes antigen presentation of tumor cells, and sensitizes tumor to cytotoxic T lymphocytes-mediated cytotoxicity." (PMID 40546938, 2025). "This places ACSL5 as a potential candidate biomarker and a promising therapeutic target, situated at the nexus of IFNγ signaling, anti-tumor immunity and alloimmunity." (PMID 40546938, 2025). "In summary, ACSL1 and ACSL4 are suspected to contribute to tumor progression in most of the tumor types examined, whereas ACSL5 appears to hinder tumor growth." (PMID 40932861, 2025). "The highly expressed AURKB in RMS contributes to the apoptosis and ferroptosis resistance of tumor cells through the nucleophosmin 1 (NPM1)/Sp1 transcription factor (SP1)/acyl-CoA synthetase long-chain family member 5 (ACSL5) axis." (PMID 39927464, 2025). "Long-chain acyl-CoA synthetase 5 (ACSL5) is found to be upregulated under glutamine deprivation, acting to sustain tumor cell viability by enhancing both glycolytic flux and oxidative phosphorylation." (PMID 41355704, 2025). "Consistently, a significant decrease in the mRNA levels of PPARa, ACLY, FASN, ACSL1 and ACSL5 was observed in the livers of C26 tumor-bearing mice compared with control mice." (PMID 38245529, 2024). "The findings indicated a positive association between the expression of ACSL5 expression and CD8+ T cell (r = 0.405, p = 3.96e‐20), CD4+ T cell (r = 0.493, p = 8.28e‐31), negativity correlated with tumor purity." (PMID 38923758, 2024). "The in vivo experiment demonstrated that the expression of ACSL5 protein was elevated in tumours of mice treated with lysoPC." (PMID 36639836, 2023). "We also found that ACSL5 is correlated with the ferroptosis signaling pathway in CM, which suggests that ACSL5 can inhibit the proliferation of tumor cells by inducing ferroptosis." (PMID 36466837, 2022). "cDNA microarray analysis further suggested that ACSL5 was critical to the expression of tumor-related factors including midkine (MDK), and the knockdown of MDK expression significantly attenuated ACSL5-mediated survival under an acidic state." (PMID 36507355, 2022). "We identified additional selective metabolic liabilities that are driven by malignant cells’ dependence on de novo fatty acid synthesis, by maximizing metabolic flux through the tumor-enriched ACSL5 reaction in our model." (PMID 32103057, 2020). "Our study showed that the panel of ACOT8/ACSL5/FASN/HMGBCS2/SCD1 genes had a better prognostic performance than validated clinical risk scales and is applicable for early detection of CRC and tumor recurrence." (PMID 32155177, 2020).
tumor (continued). "Our analysis finds that ACSL5 gene is strongly enriched in one tumor region (section 1.2), and it has been also been found to be over-expressed in other prostate cancer." (PMID 32103057, 2020). "ACSL5 involved in enterocytic differentiation and maturation has already been a predictive prognostic factor for early tumor recurrence in CRC patients." (PMID 29340021, 2017). "Study has confirmed that ACSL5 influences tumor progression via immune pathways." (PMID 41288931, 2025). "And ACSL5 has been found to function as an immune-dependent tumor suppressor." (PMID 40181462, 2025). "ACSL5 may inhibit tumor proliferation in low-grade lung tumors, while ACSL3 may enhance proliferation in high-grade lung tumors." (PMID 38539505, 2024). "In addition, a higher expression of ACSL1 and ACSL5 was significantly related to a low tumor grade (ACSL1, p = 0.023; ACSL5, p = 0.025), while a higher expression of ACSL4 was significantly associated with a high grade (p = 0.009)." (PMID 38539505, 2024). "Therefore, ACSLs member’s role in the development of different types of tumours can be diverse, finding even ACSLs with a tumour suppressor profile such as ACSL5 and ACSL645." (PMID 28894242, 2017). "Neither tumor ACSL3 nor ACSL5 expression were associated with clinical outcome (data not shown)." (PMID 39853696, 2025). "ACSL5 is nuclear-coded and expressed in the mitochondria and physiologically participates in the proapoptotic sensing of cells acting as a tumor suppressor, which could possibly explain the relatively better prognosis of cluster 2 where ACSL5 was dominantly up-regulated." (PMID 35372362, 2022). "Further analysis revealed that differentiation status, tumor stage, LOX expression, and ACSL5 expression were independent factors predicting prognosis." (PMID 39108264, 2024). "The activities of CA1, ANXA10, and MUC1 were increased in LPS treated IBD enteroids compared to the LPS treated tumor enteroids, while the activities of BAAT, ACSL5, and ENPP6 were decreased." (PMID 35884586, 2022). "In an IHC study involving 72 patients, those with reduced ACSL5 levels experienced significantly increased tumour recurrence within one year, independent of TNM and UICC stages." (PMID 41154605, 2025). "The data suggest that ACSL5 may exert a suppressive function in low-grade lung tumors, while ACSL3 may enhance tumor proliferation in high-grade tumors." (PMID 38539505, 2024). "Additionally, LPS treatment altered the ACSL5, ENPP6, and CA1 expression in the intestine and tumor enteroids." (PMID 35884586, 2022). "ACSL5 is spatially variable in tissue section 1.2 (highly expressed mainly in the tumor), while LRP1 is not (erratically expressed across the entire section)." (PMID 32103057, 2020). "Similarly, while the expression levels of ACLY, FASN, ACSL1, and ACSL5 in the liver tissues were decreased in C26 tumor-bearing mice compared with control mice without tumors, their expression levels were significantly increased in the liver tissues of the mice fed with a fenofibrate diet." (PMID 38245529, 2024). "Of ACSLs, ACSL5 was considered as the target gene, although lysoPCs may stimulate ACSL isoform activations and promote isoform‐specific biological processes, for example, ACSL1‐involved pro‐inflammation, ACSL3‐regulated androgen responsiveness or ACSL4‐and ACSL5‐related tumour suppression." (PMID 36639836, 2023).
infection (6 papers, 2014 to 2023). The state of being infected such as from the introduction of a foreign agent such as serum, vaccine, antigenic substance or organism. "ACSL5 has a preference for C16 to C20 substrates, whereas other acyl-CoA synthetases induced by infection (SLC27A2 and ACSBG2) are more active for VLCFA (C20 to C24)." (PMID 37862421, 2023). "The acyl-CoA synthetase, ACSL5, was also induced by infection." (PMID 37862421, 2023). "For ferroptosis, the significantly up-regulated proteins shared by the L. monocytogenes 10403s and M7 infection groups were Acsl5, Tf, Acsl1, Tfrc, and Lpcat3, and the significantly down-regulated proteins were Fth1 and Ftl1: neither changed significantly in the comparison group." (PMID 35682909, 2022). "In the present study, we analyzed different time points of infection and found that ACSL1, ACSL3, ACSL4, ACSL5 and ACSL6 were all recruited into the lumen of the Ct inclusion as early as 6 hpi and as late as 24 hpi." (PMID 26988341, 2016). "In this study, E. tenella infection led to intestinal mucosal damage and caecal bleeding; the ANGPTL4 gene and the ACSL5 gene can promote cell development and angiogenesis, and they were both significantly upregulated in the PPAR pathway on the seventh day after chicken infection with coccidioides." (PMID 31159150, 2019).
adenocarcinoma (2 papers, 2014 to 2024). A common cancer characterized by the presence of malignant glandular cells. "In primary lung tumors, a higher expression of ACSL1, ACSL4, and ACSL5 was significantly correlated with adenocarcinoma (ADC)." (PMID 38539505, 2024).
metabolic disease (2 papers, 2021 to 2025). A congenital disorder (due to inherited enzyme abnormality) or acquired (due to failure of a metabolically important organ) disorder resulting from an abnormal metabolic process. "The disorders known to be associated with the affected genes range from embryonic lethality (e.g., MRPL55 and LIG3) and metabolic diseases (e.g. acyl-CoA synthetase long chain family member 5 (ACSL5)) to neurodevelopmental disorders (e.g., methionyl-tRNA synthetase 2 (MARS2))." (PMID 34915862, 2021).
ACSL5 also shares sentences with these, for which no sentence is quoted: adenoma (3 papers); amyotrophic lateral sclerosis (3); Hepatic steatosis (3); brain cancer (2); Glucose intolerance (2); acute myeloid leukemia (1); adenocarcinoma of the small intestine (1); Autoimmunity (1); chronic kidney disease (1); colorectal tumors (1); developmental delay (1); endometrioid adenocarcinoma (1); glioblastoma (1); Granuloma (1); idiopathic pulmonary fibrosis (1); liver diseases (1); lung adenocarcinoma (1); metabolic dysfunction-associated steatotic liver disease (1); metastatic tumors (1); migraine (1); neurodevelopmental disorder (1); non-small cell lung carcinoma (1); pancreatic ductal adenocarcinoma (1); periampullary adenocarcinoma (1); renal carcinoma (1); rhabdomyosarcoma (1); sarcopenia (1); small intestine carcinoma (1); systemic sclerosis (1).